ENSG00000259164 (novel protein)
Gene: Protein-coding gene on chromosome 14 (77,098,311 to 77,225,462, forward strand). Ensembl gene ENSG00000259164.
Genetic constraint (gnomAD): Missense variants: 56 observed, 71.59 expected, observed/expected ratio (o/e) 0.78, 90% interval 0.63 to 0.98. Synonymous variants: 20 observed, 24.75 expected, observed/expected ratio (o/e) 0.81, 90% interval 0.57 to 1.17.